REN (renin)
Diseases named in the same sentence as REN in open-access papers (continued):
Sharing a sentence is not in itself a finding about the gene and the disease.
Hypertension (continued). "First, human studies have shown that there is a broad spectrum of autonomous and renin-independent aldosteronism and MR activation; PA is not only a disease reserved for those with severe and resistant hypertension, rather can be detected in mild to moderate hypertension and also in normotension." (PMID 29439489, 2018). "In addition to this, Angiotensin II, a key component of the renin-angiotensin system (RAS) can also enter the brain during hypertension and influence the immune system through the activation of Angiotensin type 1 receptor (AT1R) in astrocytes and microglia, of great relevance to MS progression." (PMID 29988562, 2018). "Some authors have noted several physiological changes that occur in people with excess body fat, such as activation of the sympathetic nervous system and the renin-angiotensin aldosterone system, endothelial dysfunction and/or functional abnormalities, may result in hypertension." (PMID 29478413, 2018). "In another study on double-transgenic rats, vitamin D-depleted rats were shown to exacerbate hypertension (HTN) and impact the renin-angiotensin system, which can contribute to end-organ damage." (PMID 29977597, 2018). "At a stage when drug-resistant hypertension is re-emerging potently our results can also provide a background for developing trials on the clinical use of urotensin II receptor antagonists that should consider the effects of urotensin II on renin and aldosterone, at variance with what done so far." (PMID 29066763, 2017). "Several factors are involved in the onset of hypertension after renal transplantation: immunosuppressive therapy including corticosteroids and cyclosporine, graft function, the nature of the donor, obesity, alcohol, smoking, presence of a native kidney (increased production of renin)." (PMID 29541287, 2017). "However, in the pathophysiology of hypertension, such as essential hypertension, Nox4 expression seems to be upregulated by the renin-angiotensin system, which may have harmful effects." (PMID 28591344, 2017). "Thus, part of the hypertension in the CDET-1KO mouse is due to relative renin-angiotensin-aldosterone system overactivity, and these data suggest that CD ET-1 may regulate renal renin production." (PMID 26956245, 2016). "Second, CMV might influence hypertension via regulation of the renin-angiotensin system." (PMID 26980213, 2016). "The important role of RAAS molecules in hypertension has not only been demonstrated in the adult population, healthy children with hypertensive parents also have the tendency to present a higher aldosterone-renin ratio than healthy children with normotensive parents." (PMID 27347925, 2016). "In addition, hypertension secondary to renal ischemia and activation of renin–angiotensin–aldosterone system may also occur." (PMID 27227941, 2016). "Specifically, the main determinant of hypertension in lean people is peripheral vasoconstriction, whereas obesity-related hypertension depends on sympathetic nervous system hyperactivation and on the consequent increase in cardiac output and renin and aldosterone release." (PMID 26980335, 2016). "Thus, the ability of the cod peptides to inhibit both ACE and renin activities could be used as an effective tool to modulate the renin–angiotensin system in order to treat or prevent hypertension." (PMID 26715103, 2015). "Thus, we tested the hypothesis that antenatal MLPD leads to sexually dimorphic developmental programming of the components of the pulmonary renin-angiotensin system, which may be important in the antenatal MLPD-associated development of hypertension." (PMID 25971747, 2015). "We suggest that renin-angiotensin-driven hypertension encompasses feedback and feedforward mechanisms in the development of neurogenic hypertension while low-intensity, chronic peripheral inflammation of any origin may serve as a model of a feedforward mechanism in this condition." (PMID 25935397, 2015).
Hypertension (continued). "To assess whether the hypertension in programming was mediated by dysregulation of the systemic renin-angiotensin system or if the systemic renin-angiotensin system was affected by enalapril, we measured plasma renin activity, angiotensin II and aldosterone in the 6 groups." (PMID 26719973, 2015). "The interest in bioactive peptides as agents for the control of hypertension continues to increase and our previous study has confirmed that rapeseed protein-derived peptides (Thr-Phe, Leu-Tyr and Arg-Ala-Leu-Pro) possess dual in vitro inhibitions of renin and ACE activities." (PMID 24603692, 2014). "Therefore, targeting Mets-related pathophysiological conditions, including renin-angiotensin system activation, may be an effective strategy to prevent colorectal carcinogenesis in patients with Mets, particularly those with hypertension." (PMID 24959250, 2014). "Only transient increase (at the end of the first week of treatment) of renin expression and arterial pressure in the wildtypes was observed suggesting that the conditional PPARgamma knockout mice have also limited relevance as a model for studying the hypertension in human MetS." (PMID 24288524, 2013). "Therefore, our present work not only provides a novel finding on the mechanism of disrupted circadian BP rhythm in MetS but also highlights the autonomic nervous system and renin‐angiotensin‐aldosterone system as promising therapeutic targets for hypertension complicated by MetS." (PMID 23629805, 2013). "Therefore, we hypothesised that these aged uni-x female sheep with low-renin hypertension may have an increase in expression and function of components of intra-renal RAS." (PMID 23840884, 2013). "Furthermore, I discuss the need for generating of additional transgenic animal models which are more appropriate with regard to the role of the PPARgamma-dependent regulation of the renin gene expression in human diseases such as arterial hypertension and metabolic syndrome." (PMID 24288524, 2013). "In addition, the PPARgamma-dependent transactivation of the renin gene could be one of the mechanisms inducing hypertension in obesity and its accompanying diseases, diabetes mellitus type 2 (DM2) and metabolic syndrome (MetS)." (PMID 24288524, 2013). "Sympathetic hyperactivity, activation of the renin-angiotensin-aldosterone system (RAAS), and the related development of hypertension are implicated; and this may be further aggravated by excess dietary salt intake and effects of insulin resistance and hyperinsulinemia on sodium retention." (PMID 22537670, 2012). "Fat mass could lead to hypertension by different mechanisms, namely by activating the renin–angiotensin–aldosterone system, increasing sympathetic activity, promoting insulin resistance and leptin resistance and increasing procoagulatory activity and endothelial dysfunction." (PMID 23190867, 2012). "Furthermore, high sodium consumption and hyper caloric diets may also lead to hypertension and to diabetes mellitus, obesity and perturbation of the renin-angiotensin-aldosterone system, impairing vascular tone and increasing endothelial dysfunction." (PMID 23194345, 2012). "Studies indicated that in early phase of 2K1C hypertensive animals, increased activity of PRA and renin-angiotensin-aldosterone is responsible for increasing blood pressure, however, after 8 week of clipping, change of endothelial function is importance regarding hypertension." (PMID 23493527, 2011). "Excessive expression of COX-2 as observed in this study may stimulate renin-angiotensin-aldosterone system and as suggested by others lead to increased arterial pressure and vascular lesions in inflammatory diseases, including hypertension and diabetes." (PMID 21492462, 2011). "Likewise, the renin–angiotensin–aldosterone system may have initially been adapted for sodium conservation but may play an important role in the pathogenesis of hypertension in modern societies with high dietary salt intake." (PMID 20035862, 2010).
Hypertension (continued). "Endothelial NO synthase (eNOS) expression and activity were down-regulated while ACE and AT1 receptor expression were up-regulated in the left ventricle of DOCA-salt rats suggesting that the local renin-angiotensin and NO systems may be unfavourably modulated in this model of hypertension." (PMID 22043205, 2010). "Hypertension, as a vascular complication of DM, is frequently seen in Type I DM and many factors are involved in its pathogenesis including the availability of nitric oxide, increased production of ROS and alterations in the renin-angiotensin system as well as dyslipidaemia." (PMID 20465785, 2010). "Given the importance of the renin-angiotensin system in long-term blood pressure regulation, further characterisation of the genetic determinants of circulating ACE has the potential to improve our understanding of the mechanisms underlying the development of high blood pressure." (PMID 18544166, 2008). "Again, spironolactone has been shown to improve the parasympathetic component of heart rate variability and it is of interest to examine if this is also the case in hypertension and whether such an effect is more prominent in subjects with a high aldosterone: renin ratio." (PMID 17490489, 2007). "However, patients with high aldosterone: renin ratios tend to have resistant hypertension." (PMID 17490489, 2007). "In essential hypertension, a similar dose-response relationship is true for spironolactone but higher doses of spironolactone may reduce BP more in those with high aldosterone: renin ratios." (PMID 17490489, 2007). "Conversely, in patients with atrial fibrillation the renin–angiotensin–aldosterone system (RAAS) is activated because of reduced cardiac function and hypertension." (PMID 41608286, 2026). "Hypertension frequently coexists with OSA, with evidence supporting OSA-driven hypertension mediated by sympathetic overactivity, RAAS (renin-angiotensin-aldosterone system) activation and endothelial dysfunction." (PMID 41903652, 2026). "Her initial work-up during nicardipine and furosemide infusion showed a normal aldosterone-to-renin ratio (ARR), leading to misdiagnosis as essential hypertension." (PMID 41661122, 2026). "The role of the renin-angiotensin system (RAS) is widely acknowledged in the development and progression of hypertension." (PMID 40351692, 2025). "Of these, only the aliskirin (a renin inhibitor) and losartan (an ARB) have been specifically evaluated for its reprogramming effects against hypertension programmed by maternal high-fructose diets in offspring." (PMID 39911806, 2025). "Although rare, hypertension can be the initial manifestation of UPJO, resulting from activation of the renin-angiotensin system due to chronic obstruction." (PMID 41030762, 2025). "Decreased renal perfusion leads to the release of renin and in turn activates the renin‐angiotensin‐aldosterone system (RAAS), which promotes hypertension and triggers a cascade of events." (PMID 40364719, 2025). "Evidence demonstrates that oxidative stress and the renin-angiotensin-aldosterone system (RAAS) activation serve as strong mechanisms linking osteoporosis and hypertension." (PMID 41431547, 2025). "Patients with hypertension with an elevated screening ARR and a low renin, but normal aldosterone suppression during confirmatory test, are considered to have a subtle form of PA and are typically managed with mineralocorticoid receptor antagonist." (PMID 39911522, 2025). "RASIs, such as direct renin inhibitors, angiotensin II receptor blockers (ARBs), and angiotensin-converting enzyme inhibitors (ACE-Is) are frequently used to manage hypertension and heart failure." (PMID 41417371, 2025). "In a rat model of hypertension, an n-3 PUFA-enriched diet attenuated arterial hypertension induced by the renin–angiotensin–aldosterone system (RAAS)." (PMID 39601825, 2025).
Hypertension (continued). "Men typically have a higher percentage of visceral fat percentage, which is associated with increased sympathetic nervous system activation, renin–angiotensin–aldosterone system (RAAS) stimulation, and oxidative stress, all of which contribute to hypertension." (PMID 40427867, 2025). "Briefly, the kidney cells responsible for renin production (juxtaglomerular cells) are sensitive to calcitriol, and VDR and CYP27B1 knock-out mice develop high renin systemic hypertension which can be rescued with angiotensin converting inhibitors." (PMID 40448712, 2025). "The most studied ones are part of the renin–angiotensin system (RAS), which regulates blood pressure and salt homeostasis and has a role in hypertension development." (PMID 40149592, 2025). "Abnormal renal lipid metabolism, such as cholesterol crystal deposition in renal tubules, can activate the renin-angiotensin system (RAS), promoting hypertension and renal fibrosis, thereby forming a vicious cardiorenal cycle." (PMID 40661082, 2025). "In patients with hypertension or unexplained hypokalemia, the ESE/ENSAT guidelines recommend screening using the aldosterone-to-renin ratio (ARR) under standardized conditions, followed by confirmatory testing when indicated." (PMID 41007858, 2025). "Human renin from the fetus crosses the placenta to cleave human angiotensinogen that cannot be cleaved by rat renin, resulting in increased angiotensin II, AT1-AA production and hypertension." (PMID 40777009, 2025). "Concerning the optimal mineralocorticoid dose, some authors recommend using a combination of Plasma-renin-activity (PRA), sodium-to-potassium ratio, assessment of hypertension, and clinical signs to guide DOCP therapy." (PMID 41560860, 2025). "The aim of this systematic review is to evaluate the comparative effectiveness of direct renin inhibition versus ACEi and ARB therapy in patients with hypertension." (PMID 41409925, 2025). "Angiotensin II (Ang II), a key hormone of the renin-angiotensin system (RAS), plays a crucial role in the pathophysiology of hypertension." (PMID 40567422, 2025). "This narrative review explores the pathophysiological underpinnings of nocturnal hypertension in CKD, including impaired sodium handling, volume overload, autonomic dysfunction and dysregulation of the renin–angiotensin–aldosterone system." (PMID 40927380, 2025). "FMD can cause hypertension even with moderate stenosis, possibly through localized changes in renal perfusion and activation of the renin-angiotensin-aldosterone system (RAAS), but one might not expect severe, refractory hypertension from a 30% narrowing alone." (PMID 41356982, 2025). "The renin-angiotensin system (RAS) plays a central role in hypertension pathogenesis, while excessive sympathetic activation contributes to both hypertension and end-organ damage." (PMID 40351606, 2025). "The etiology of hypertension in ADPKD is multifactorial, involving activation of the renin-angiotensin-aldosterone system (RAAS), increased sympathetic activity, and vascular dysfunction mediated by endothelin and nitric oxide imbalances." (PMID 40268755, 2025). "Here, we induced hypertension in aged C57BL/6J mice by infusing Ang II, a potent vasoconstrictor component of the renin–angiotensin–aldosterone system (RAAS)." (PMID 40045320, 2025). "Therefore, it is hypothesized that the reduced levels of vitamin D and VDR observed in keloids may weaken the regulatory effect of vitamin D on the renin–angiotensin system (RAS), thereby promoting the development of hypertension and potentially increasing the risk of keloid formation." (PMID 40836860, 2025). "The regulation of hypertension involves multiple mechanisms, including the SNS, renin–angiotensin–aldosterone system (RAAS), and central and peripheral autonomic cardiovascular regulatory systems." (PMID 41341616, 2025).
Hypertension (continued). "High blood pressure (hypertension) is usually regulated by angiotensin-converting enzyme (ACE) via the kinin-kallikrein system (KKS) and the renin-angiotensin-aldosterone system (RAAS)." (PMID 41209547, 2025). "Using aldosterone–renin quotient (ARQ) screening, the prevalence of PA in primary-care patients treated for hypertension is approximately 4–13%." (PMID 39595045, 2024). "In the succeeding paragraphs, we highlight the pertinent findings of renin, AGT and ACE SNPs in relation to PE, PIH and hypertension." (PMID 38411777, 2024). "For the 5-year follow-up model, essential features included age, renin-angiotensin system medications, hyperlipidemia, triglyceride levels, CCI score, gender, antithrombotic drugs, stroke history, hypertension, and calcium-channel blockers." (PMID 39434474, 2024). "Local levels of succinate in the kidney activate the renin–angiotensin system, thus contributing, through GPR91, to developing hypertension and the complications of diabetes mellitus, metabolic disease, and liver damage." (PMID 38397087, 2024). "The renin–angiotensin–aldosterone system (RAAS) and its significant classical role in the occurrence of arterial hypertension was first discussed in the 1960s." (PMID 39062156, 2024). "Overactivation of the renin–angiotensin system (RAS) plays a critical role in the aging process and the age-related pathogenesis of many diseases, including hypertension and AD." (PMID 39000445, 2024). "The regulation of hypertension involves the renin–angiotensin system (RAS) or renin–angiotensin–aldosterone system, which is essential for controlling peripheral hypertension through ACE-I activity." (PMID 38746020, 2024). "Given Ang II as the key component of the renin-angiotensin system, NFKB activation is critically involved in the development of hypertension." (PMID 39592923, 2024). "Angiotensin II is a major peptipe effector of the renin-angiotensin (RAS) system, promoting hypertension, even proliferation and invasion of the tumor cells." (PMID 38355782, 2024). "In our young rat model of CKD-induced hypertension, RBE treatment decreased renin and AT1R levels in the classical RAS axis while increasing ACE2, MAS, and AT2R levels in the nonclassical axis." (PMID 39683469, 2024). "The renin–angiotensin–aldosterone system, primarily Ang-II via AT1 receptors (AT1-R), plays a major role in promoting hypertension, development of LV hypertrophy, and progression to HF." (PMID 38397106, 2024). "The lower kidney renin is important to the legacy of early RAS inhibition in SHR because of the major role of the RAS in BP homeostasis and for the pathophysiology of SHR hypertension." (PMID 38501595, 2024). "It is reported that melatonin restrains programmed hypertension resulting from neonatal dexamethasone (DEX) exposure that increases HDAC 1–3 protein levels and inactivates most renin–angiotensin system (RAS) genes in the kidney." (PMID 39519150, 2024). "In the case of hypertension, epigenetic changes are influenced by intrauterine environmental factors that may impair nephron development, as well as by factors affecting autonomic responsiveness, vascular remodeling, salt sensitivity, and the renin-angiotensin system." (PMID 39713213, 2024). "Multiple mechanisms, including the sympathetic nervous system, the renin-angiotensin-aldosterone system (RAAS), and endothelial dysfunction, are involved in the pathophysiology of both kinds of hypertension." (PMID 39171117, 2024). "At the same time, the presence of important components of the renin–angiotensin system at the adipocyte level could have detrimental cardiovascular effects in people with obesity, which could lead to the creation of a vicious circle of obesity–arterial hypertension–diabetes–atherosclerosis." (PMID 39062156, 2024). "Medications that block each step of the RAAS mechanism, including renin inhibitors, ACE inhibitors, and Ang II type 1 receptor antagonists, are currently used in the treatment of hypertension." (PMID 39125672, 2024).